STAT3 (signal transducer and activator of transcription 3)
Diseases named in the same sentence as STAT3 in open-access papers (continued):
Sharing a sentence is not in itself a finding about the gene and the disease.
Sepsis (continued). "In both control and OVR females, sepsis increased the myocardial expression of genes encoding protein associated to inflammation, interleukin-6 (IL-6), IL-10 and IL-18, to cell cycle and survival, Janus Kinase 2 (JAK2) and signal transducer and activator of transcription 3 (STAT3)." (PMID 35322092, 2022). "However, the potential therapeutic value of targeting mitochondrial STAT3 with inhibitors in individuals with sepsis remains unknown." (PMID 34976224, 2022). "This suggests that JAK2 may serve as an upstream kinase of STAT3 during CLP-induced sepsis." (PMID 32943679, 2020). "Hence, in sepsis, STAT3 also mediated HIF-1α transcriptional activity in its signaling pathway." (PMID 32089644, 2020). "Interestingly, previous studies on the function of lncRNA DILC in development of diseases revealed that it was down-regulated during tumorigenesis and sepsis and functioned as a suppressor gene in cancer development and sepsis, which depends on its suppressive effect on STAT3 activation." (PMID 32510145, 2020). "While appreciating that several crucial issues, including safety and adverse effects, have to be addressed in further study, our results suggest that STAT3 suppression with the use of transcription decoy strategy may represent a novel and efficacious therapeutic option for sepsis treatment." (PMID 32943679, 2020). "lncRNA MCM3AP-AS1 alleviates sepsis-induced cardiomyopathy by improving inflammation, oxidative stress, and mitochondrial function through the inhibition of the miR-501-3p/CADM1/STAT3 axis." (PMID 40041174, 2025). "In sepsis, the JAK2/STAT3 pathway is specifically induced by IL-6, thereby initiating the proinflammatory effects of this cytokine through the generation of IL-6 trans-signaling." (PMID 39955435, 2025). "For instance, mitochondrial STAT3 can trigger fatty acid oxidation by inducing the stabilization of CPT1a mediated by USP50 in macrophages, exacerbating LPS-induced sepsis." (PMID 40766066, 2025). "When sepsis occurs, the inflammatory factors IL-6 and TNF-α released at the early stage in the body can bind with STAT3, activate it, and enhance IL-6 and TNF-α transcription in the nucleus." (PMID 40338919, 2025). "At the same time, during the development of sepsis, the expressions of JAK2 and STAT3 proteins were significantly up-regulated, and the transcription and expression of downstream inflammatory factors IL-6 and TNF-α were also increased." (PMID 40338919, 2025). "Concurrently, in a sepsis study, Pectolinarigenin mitigate sepsis-induced kidney injury by inhibiting the JAK2/STAT3 pathway." (PMID 39955435, 2025). "The AUROCs for diagnosing sepsis using MAPK8, PTEN, PPARG, and STAT3 were calculated as 0.808 (95% CI 0.586–1.000), 0.842 (95% CI 0.643–1.000), 0.883 (95% CI 0.713–1.000), and 0.85 (95% CI 0.652–1.000), respectively." (PMID 40070882, 2025). "ATP-P2X7 activation by sepsis involves IL-6 production and STAT-3 activation in the brain, and P2X7R blockade has been found to diminish STAT3 activation in the cerebral cortex and hippocampus." (PMID 38585633, 2024). "This failure, characterized by less STAT3 phosphorylation and less APP production mediated by C/EBPβ and STAT3, can be attributed to the HNF4α LOF in sepsis and contributes to the lethality of CLP." (PMID 39261648, 2024). "We found that shared biological pathways, especially checkpoint, cytolytic activity, IL6/JAK/STAT3 signaling, and TLR pathway were significantly correlated with most of the infiltrating immune cells in sepsis and trauma." (PMID 38384415, 2024). "Salidroside ameliorate CLP-induced pulmonary fibrosis in mice with acute lung injury from sepsis by downregulating p-JAK2 and p-STAT3 protein expression; also by regulating collagen-related protein." (PMID 38567353, 2024). "HNF4α dysfunction also interferes with interleukin 6 (IL6)-induced, C/EBPβ and STAT3 controlled induction of APR genes and proteins, and hence interferes with liver regeneration in lethal sepsis." (PMID 39261648, 2024).
Sepsis (continued). "Additionally, inhibiting the JAK/STAT3 signaling with piceatannol could improve sepsis-induced cardiac dysfunction by relieving cell apoptosis and inflammation in septic mice and H9C2 cardiomyocytes, suggesting a critical role of the JAK/STAT3 pathway in sepsis-related myocardial injury." (PMID 38495094, 2024). "Collectively, these data suggest that the sepsis-induced decrease in Malat1 expression promotes the expansion and immunosuppression of PMN-MDSCs by enhancing STAT3 phosphorylation." (PMID 38385073, 2024). "The result is a reduction in the relative expression of signal transducer and activator of transcription 3 (STAT3) and glutathione peroxidase 4 mRNA with effects to be evaluated in the clinical setting in the management of patients with sepsis." (PMID 39768830, 2024). "Our data showed that persistent low Malat1 expression in late sepsis promotes the expansion and activation of PMN-MDSCs by maintaining the phosphorylation of STAT3." (PMID 38385073, 2024). "The activation of STAT3 and elevated protein level of iNOS were also detected in PMN-MDSCs from mice with late sepsis." (PMID 38385073, 2024). "Eight genes (CLEC5A, MALT1, NAIP, NLRC4, SERPINB1, SIRT1, STAT3, and TLR2) related to sepsis diagnosis were screened by multiple machine learning algorithms." (PMID 36817458, 2023). "Coincidentally, a recent publication has shown that XBJ can improve sepsis-induced myocardial damage and inflammation by regulating the NF-κB and JAK2/STAT3 pathways." (PMID 38094883, 2023). "We further investigated the protective role of MF against SAT in a mouse model of cecal ligation and puncture (CLP)-induced sepsis, focusing on the JAK2/STAT3 signaling pathway in the liver." (PMID 37240208, 2023). "Baicalin regulated multiple members of the STAT family, including STAT1, STAT3, STAT4, and STAT5, for treating T2D-induced liver tumor, sepsis, and myocardial ischemia reperfusion injury." (PMID 36324680, 2022). "To study the function of mitochondrial STAT3, we injected mice from the same littermate intraperitoneally with 4-OHT followed by LPS to induce a murine sepsis model." (PMID 34976224, 2022). "In the experimental sepsis model, hyperactivation of STAT1 and STAT3 in the macrophages and monocytes induces immune system dysfunction and excessive release of inflammatory factors, resulting in sepsis-induced heart injury." (PMID 36619743, 2022). "miR-21 and miR-181b promotes MDSCs generation by targeting STAT3 and C/EBP in sepsis-induced inflammatory response, while when inhibiting these miRNAs, the number of MDSCs is reduced and the late-sepsis survival was significantly enhanced." (PMID 36569895, 2022). "Early-stage AKI, based on Kidney Diseases Improving Global Outcomes (KDIGO) AKI criteria, was established and used to examine the role of STAT3 signaling in cecal ligation and puncture (CLP) sepsis model." (PMID 35733865, 2022). "Rationale: We found that a subset of signal transducer and activator of transcription 3 (STAT3) translocated into mitochondria in phagocytes, including macrophages isolated from individuals with sepsis." (PMID 34976224, 2022). "This assumption is supported by the cooperation between TNFα-induced NF-κB and the JAK/STAT3 pathway which has recently been demonstrated in brain pericytes, and by the inhibitory effects of TCZ on NF-κB in a rat model of sepsis." (PMID 34975837, 2021). "Sepsis induced JAK1 phosphorylation, followed by STAT3 phosphorylation, which activated the JAK1/STAT3 signaling pathway." (PMID 33506010, 2021). "We consider that GDF15 plays a protective role in sepsis; it can inhibit the M1 polarization of macrophages as well as the phosphorylation of JAK1/STAT3 signaling pathway and nuclear translocation of NF-κB p65 to alleviate inflammation." (PMID 34566964, 2021).
Sepsis (continued). "We generated phosphorothioate double-stranded ODNs, which contains two binding sites for STAT3 recognized in the stem region in the DNA structure, and in vivo introduced into mice with CLP-induced sepsis." (PMID 32943679, 2020). "As SOCS3 can inhibit the IL-6/STAT3 pathway, ADAR1 is expected to reduce IL-6 levels by regulating the expression of SOCS3, thereby inhibiting inflammation and alleviating sepsis." (PMID 32273831, 2020). "Moreover, the JAK2/STAT3 and NF-κB signaling pathway might be involved in sepsis-induced AKI." (PMID 31084615, 2019). "It is not unexpected that signaling conducted by various STATs, particularly STAT3, will be closely interconnected with NF-κB signaling—the nuclear factor responsible for managing the production of proinflammatory mediators in ALI, sepsis, and systemic shock." (PMID 31780865, 2019). "In summary, our work shows that insulin administration displays critical liver and glucose metabolism protective roles in sepsis rat models, possibly through suppression of NF‐κB pathway and neuropeptide POMC‐mediated inhibition of STAT3 in liver." (PMID 29285858, 2018). "In sepsis rats, hepatic IKK/NF‐κB pathway and STAT3 were strongly activated, along with reduced body weight, blood glucose and suppressed hepatic gluconeogenesis (GNG)." (PMID 29285858, 2018). "In fact, blocking STAT3 activation using a cell-permeable STAT3 SH2 domain mimetic peptide (SIP) reduced muscle wasting in mice undergoing cancer cachexia and sepsis." (PMID 27330885, 2016). "Here we studied the role of the thyroid hormone receptors (TRs) in activation of STAT3, NF-κB and ERK, which play a key role in the response to inflammatory cytokines during sepsis." (PMID 27484112, 2016). "Sepsis increased the percentages of both CD34+ CD38− and CD34+ CD38+ with phosphorylated STAT3 and this effect was diminished by DAPT treatment, suggesting partial crosstalk between these two pathways." (PMID 26272069, 2015). "Here, we identify novel cooperative actions of STAT3 and GSK3 that control IL-6 production by glia during sepsis-induced neuroinflammation." (PMID 19284588, 2009). "The S100A4/STAT3 axis promotes AEC‐II‐derived exosomal Rmrp expression and enhances the inhibitory effect of AEC‐II‐derived exosomes on the immune responses and glycolysis of AMs following sepsis." (PMID 41178622, 2026). "We aim to determine whether Fas suppresses the STAT-3 and NLRP-3 pathways, which are crucial to sepsis-related inflammation and immune responses." (PMID 40699739, 2025). "Additionally, THCQ has been found to regulate critical target genes in sepsis patients (such as MAPK14, MAPK3, MMP9, STAT3, and LYN), which play key roles in cellular inflammatory responses, especially through the modulation of the MAPK and Nrf2 pathways." (PMID 40963685, 2025). "At early stage of sepsis, referred to as systemic hyperinflammatory response syndrome (SIRS), cytokines including tumor necrosis factor α (TNF‐α), interleukin (IL)‐1, IL‐2, IL‐6, are significantly elevated, which results in aberrant STAT3 activation." (PMID 41042728, 2025). "The present study, based on the mouse models of sepsis-induced acute lung injury, explored whether lidocaine exerts an anti-inflammatory effect by regulating the JAK2/STAT3 pathway and whether it can affect the apoptosis of lung cells." (PMID 40338919, 2025). "CS and IL-6 related signaling pathways transduction are considered as crucial factors involved in sepsis, such as upregulation of IL-6/JAK/STAT3 signaling promotes the progression of sepsis, involvement of IL-6 signaling pathway in the pathogenesis of MOF and other hyperinflammatory diseases." (PMID 39891057, 2025). "Considering the Malat1-STAT3-PMN-MDSC axis, we speculated that inhibiting STAT3 activation may have an impressive therapeutic effect on late sepsis, which was supported by our results." (PMID 38385073, 2024).
Sepsis (continued). "Together, those data showed that S100A8/A9 may function via p38/STAT3/ERK and apoptosis signalling in sepsis-induced pulmonary vascular leakage." (PMID 37978525, 2023). "Given that IL-6 is an established therapeutic target and Stat3 is an emerging target in managing sepsis, this is important for understanding the working mechanism of ACT001 in sepsis." (PMID 38094883, 2023). "The boxplot revealed 26 differentially expressed genes between the sepsis-induced ALI and control samples: Ncf2, Slc2a6, Cd44, Txnip, Slc2a1, Ubc, Hspb1, Zfp36, Arntl, Ddit4, Tnfaip3, Txnrd1, Mt1, Hmox1, Gch1, Gclc, Stat3, Egfr, Hif1a, Bach1, Socs1, Dusp1, Cdkn1a, Fth1, Steap3, and Alox12." (PMID 37081490, 2023). "In addition, methotrexate (MTX), an anti-inflammatory agent that inhibits the JAK2/STAT3 pathway, has been shown to ameliorate systemic inflammation and lung injury in a rat model of CLP sepsis." (PMID 35726235, 2022). "When sepsis develops, inflammatory molecules such as TNF-α and IL-6 may bind to signal transducers and activators of transcription 3 (STAT3) due to early inflammation in the body." (PMID 35890197, 2022). "Moreover, the downstream TFs targeted by the LR pairs in sepsis-induced ARDS are FOS, RB1, STAT2, and STAT3." (PMID 35222683, 2022). "Through the tests by western blot of STAT1 and STAT3, it revealed that the phosphorylation levels of STAT1 and STAT3 in the spleens of aged sepsis model rats were greatly increased at all time points compared with those in the spleens of normal rats, and maximal phosphorylation was observed at 24 h." (PMID 35197984, 2022). "Furthermore, we analyzed the downstream TFs targeted by LR pairs and found that different TFs, including SMAD3, RBPJ, and MAX, were targeted in sepsis-only patients, while FOS, STAT3, STAT2, and RB1 were targeted in sepsis-induced patients." (PMID 35222683, 2022). "In summary, our study found that GDF15 has good clinical application value in sepsis and plays a protective role in the development of sepsis by regulating the functions of macrophages and inhibiting the activation of JAK1/STAT3 pathway and nuclear translocation of NF-κB p65." (PMID 34566964, 2021). "Moreover, at the transcriptional level, Jun can enhance the production of inflammatory cytokines in sepsis-induced ALI, and STAT3 activated by IL-6 also contributes to the progression of ALI." (PMID 34721017, 2021). "Here, we report that phospho-Tyr705 of STAT3 (pY-STAT3), not total STAT3, contributes to systemic inflammation and coagulopathy in sepsis." (PMID 32641132, 2020). "Our findings imply that STAT3 is critical for the production of different pro-inflammatory mediators, including TNF-α, IL-1β, IL-6, and MCP-1, in CLP-induced sepsis, although STAT3 would work coordinately with other transcriptional co-activators or transcription factors." (PMID 32943679, 2020). "Therefore, reduced STAT3 activation might be involved in the increased mortality in hyperthyroid mice and a reduced response of the hepatic and/or extra-hepatic cells to this cytokine could represent a defence mechanism by which these animals could try to constrain sepsis-induced mortality." (PMID 27484112, 2016). "Inhibition of JAK2 and STAT3 tyrosine phosphorylation may reduce TNF-α level in sepsis in vivo, indicating TNF-α is also involved in the JAK2/STAT3 pathway in anti-inflammation." (PMID 23840548, 2013). "Accumulating evidence suggests that the cross-talking of JAK2/STAT3 (p-JAK2 and phospho-Tyr705) with other pathways such as NF-κB (p-IKKα/β, p-IκBα and p-P65), MAPK (p-JNK, pJun, p-P38 and p-ERK1/2), AKT (p-AKT), TLR4, mediate hyperinflammatory factor production during sepsis." (PMID 41042728, 2025).
Sepsis (continued). "Furthermore, FES knockout (FES-/-) mice demonstrate dysregulation of signal transducer and activator of transcription 3 (STAT3), which plays a vital role in the pathophysiology of sepsis by initiating endothelial dysfunction, vasoplegia, coagulopathy, and multi-organ failure." (PMID 37122758, 2023). "ER stress can increase the phosphorylation of signal transducer and activator of transcription 3 (STAT3) and monoclonal antibody to Suppressor of Mothers against Decapentaplegic (SMAD) family member 3 (Smad3), and also activate UPS‐mediated proteolysis to promote sepsis‐induced muscle atrophy." (PMID 37415097, 2023). "Thus, it is plausible that the molecular mechanisms of the protective effect of colivelin in sepsis may be related to increased AMPK, which in turn inhibits phosphorylation of STAT3." (PMID 36119052, 2022). "At the same time, GDF15 could alleviate the inflammatory response by regulating the function of macrophages and reducing the phosphorylation of JAK1/STAT3 and the nuclear translocation of NF-κB p65, which confirmed that GDF15 played a protective role in sepsis from the cellular level." (PMID 34566964, 2021). "We finally investigated whether the STAT3 inhibitor stattic could mimic the beneficial effects of STAT3 decoy ODN transfection on pro-inflammatory cytokine upregulation and organ injury in mice with CLP-induced sepsis." (PMID 32943679, 2020). "We investigated whether in vivo introduction of synthetic double-stranded STAT3 decoy oligodeoxynucleotides (ODNs) can provide benefits for reducing organ injury and mortality in mice with cecal ligation and puncture (CLP)-induced polymicrobial sepsis." (PMID 32943679, 2020). "On the contrary, exosomes released from miR-223-absent MSCs contain higher levels of Sema3A and Stat3, which might be delivered to macrophages and cardiomyocytes, leading to promotion of macrophage inflammation and cardiomyocyte death in sepsis." (PMID 26348153, 2015). "Thus, in the present study, we utilized the cecal ligation and perforation (CLP) murine model, a classic model of SI‐AKI, to assess whether the progression of sepsis‐induced renal injury is epigenetically regulated by PRMT1 through the TGF‐β1/Smad3 and IL‐6/STAT3 pathways." (PMID 37525933, 2023). "Similar to sepsis-derived MDSCs, the protein level of p-STAT3 also increased gradually while suppressors of cytokine signaling 3 (SOCS3) which was an inhibitor of STAT3 pathway did not change significantly in induced MDSCs." (PMID 38385073, 2024). "Our data showed that STAT3 was significantly activated from CLP day 1, while Malat1 expression changed with the progression of sepsis, suggesting that Malat1 may not directly affect STAT3 activation." (PMID 38385073, 2024).